KRT14 (keratin 14)
Diseases named in the same sentence as KRT14 in open-access papers (continued):
Sharing a sentence is not in itself a finding about the gene and the disease.
triple-negative breast carcinoma (11 papers, 2012 to 2025). An invasive breast carcinoma which is negative for expression of estrogen receptor (ER), progesterone receptor (PR), and human epidermal growth factor receptor 2 (HER2). "EZH2, a driver of invasiveness in multiple cancer types, upregulates KRT14 through the H3K27me3 mechanism to enhance peritoneal metastasis in triple-negative breast cancer (TNBC), suggesting that targeted inhibition of EZH2 could potentially impede TNBC metastasis." (PMID 39043634, 2024). "Triple negative breast cancers (TNBCs) are known to express low PGR, ESR1, and ERBB2, and high KRT5, KRT14, and KRT17." (PMID 30335837, 2018). "On the other hand, the C19MChigh group harbored significantly upregulated expression of KRT5, KRT14 and KRT17 mRNAs compared to C19MClow group, the candidate “positive markers” of basal-like triple negative breast cancers (TNBCs)." (PMID 30335837, 2018). "Several basal-related genes directly corresponding to expression levels of cytokeratins and EGFR protein marker, including KRT5, KRT6C, KRT6E, KRT14, and EGFR genes, were found to be extensively up-regulated in triple-negative breast cancer." (PMID 23049873, 2012).
epidermolysis bullosa (10 papers, 2013 to 2024). Epidermolysis bullosa (EB) is a group of genetic skin diseases that cause the skin to blister very easily. "To study the contribution of keratins, we overexpressed a dominant mutation of keratin 14, namely, K14-R125C, identified in some epidermolysis bullosa patients." (PMID 39468334, 2024). "For example, mutations in KRT5 and KRT14 can cause epidermolysis bullosa to a large extent." (PMID 30781701, 2019). "Our study reveals that Epidermolysis Bullosa patients with COL7A1 c.6163G > A and KRT14 c.377T>A variants have different clinical presentations, with dominant forms of Dystrophic EB having milder phenotypes than recessive ones." (PMID 38580989, 2024). "Many promising results have been published using the CRISPR/Cas9 technology to efficiently correct mutations in epidermolysis bullosa, especially for mutations in COL7A1, COL17A1, KRT5 and KRT14." (PMID 36901775, 2023). "Additionally, two unrelated patients with BS I and epidermolysis bullosa shared identical homozygous FKBP10 and KRT14 variants." (PMID 38927610, 2024).
urothelial carcinoma (10 papers, 2015 to 2024). A malignant neoplasm derived from the transitional epithelium of the urinary tract (urinary bladder, ureter, urethra, or renal pelvis). "Using two oncogenes and the epithelium-specific promoters KRT14 and Cdh1 resulted in the most frequent growth of orthotopic urothelial carcinoma of all experimental groups." (PMID 39463382, 2024). "KRT14 has been described before as a marker of basal cells with stem cell characteristics that represents the most primitive differentiation state of urothelial carcinoma." (PMID 36831256, 2023).
bladder tumors (9 papers, 2016 to 2025). "Interestingly, basal bladder tumors express high levels of genes typical of more undifferentiated urothelial basal cells (KRT5, KRT6, and KRT14) together with several transcription factors that support stem cell homeostasis and cancer progression also presented a CD44shigh phenotype." (PMID 35547758, 2022).
lung carcinoma (9 papers, 2016 to 2025). "Keratin 14 (KRT14) is a conserved epithelial marker of the LC subset across many epithelial malignancies including breast, bladder, ovarian, and lung cancers." (PMID 39408880, 2024). "Lung cancer KRT14+ LCs co-express gastrokine 1 (Gkn1) which enhances their metastatic potential by supressing Akt and inhibiting cell death via anoikis." (PMID 39408880, 2024). "KRT14 enhances the metastatic potential of lung cancer cells, promotes cell invasion of salivary adenoid cystic carcinoma, and is also correlated with worse patient prognosis." (PMID 36949761, 2023). "A high level of GKN1 protein, with which Keratin 14 (K14) - high cancer cells could resist anoikic, plays a vital role in promoting metastasis of lung cancer cells with low K14 expression." (PMID 38250608, 2024). "Prognostic associations of KRT5 and KRT14 have been implicated in lung cancer, while the relationship and molecular mechanisms of KRT6A and KRT17 in the lung cancer are still unknown and should be further elucidated." (PMID 27684953, 2016). "For example, KRT5, KRT6A, KRT14, and DSG3 in LUSC25, and NKX2.126, SFTA227 in LUAD have been evidently proved directly correlated to the lung cancer diagnosis and progression." (PMID 40654610, 2025). "For example, KRT5,KRT6A, KRT14, and DSG3 (All of these genes shown are with an adjustedp-value < 1e–200) in LUSC, and NKX2.1, SFTA2 (All of these genes shown are with anadjusted P-value < 1e–200) in LUAD have beenevidently proved directly correlated to the lung cancer diagnosis andprogression." (PMID 41347120, 2025).
dysplasia (8 papers, 2013 to 2022). A usually neoplastic transformation of the cell, associated with altered architectural tissue patterns. "Transgenic hemizygous mice expressing the complete early genome region (CER) of the betaHPV type 8 (HPV8) under the control of the human keratin-14 (K14)-promoter (referred to as K14-HPV8-CER) develop skin tumours, partially with moderate to severe dysplasia." (PMID 35406439, 2022).
invasive ductal carcinoma (8 papers, 2006 to 2023). "We next examined the frequency of KRT14 expression in KRT19+ cells in premalignant and malignant breast lesions, such as ductal carcinoma in situ (DCIS; n = 5) and invasive ductal carcinomas (IDC; n = 6)." (PMID 35187501, 2021).
cervical cancer (7 papers, 2011 to 2026). A primary or metastatic malignant neoplasm involving the cervix. "K14.E7 mice (E7), derived from C57/B6 mice (B6), express HPV E7, a major oncoprotein in HPV-related cervical cancer, from the keratin-14 promoter." (PMID 29464051, 2018).
pancreatic cancer (7 papers, 2018 to 2025). "Publicly available datasets revealed a positive correlation between KRT14 and TP63 in lung, cervix, oesophagus and pancreatic tumours." (PMID 32128997, 2020). "Overall, these findings show that ERK3 expression is linked to the expression of key partial-EMT markers in breast and pancreatic cancer—SNAIL, KRT14, and YAP—and it regulates the expression of protumour proteins such as β-catenin and CYR61 in a cancer type-dependent manner." (PMID 40936697, 2025). "Importantly, we also demonstrated that ERK3 appears to have a similar modulatory role in EMP in other types of cancer, specifically lung and pancreatic cancer, including a promigratory effect and regulation of SNAIL, KRT14, YAP, CYR61, and β-catenin." (PMID 40936697, 2025).
prostate carcinoma (7 papers, 2009 to 2024). A carcinoma that arises from epithelial cells of the prostate gland. "Finally, we noticed that basal epithelial cells' marker cytokeratin 14 mRNA levels did not present any variations between androgen-independent prostate cancer and BPH (except for sample C2 for which no information is available to allow an explanation for its non-detection)." (PMID 19763272, 2009).
colitis (6 papers, 2014 to 2025). Inflammation of the colon. "The decreased expression of Krt-14 following colitis may be attributed to an impaired intestinal barrier." (PMID 39865190, 2025). "ScRNA-seq analysis also revealed that a new skin-like epithelial population called squamous neo-epithelium marked by the expression of Sox2/Krt14/Krt7 could confer the resistance to colitis injury and rebuild the epithelial structure after colitis." (PMID 36045190, 2022).
metastatic tumor (6 papers, 2007 to 2024). "In addition, myoepithelial markers (e.g. p63, cytokeratin 14, and calponin) and endothelial markers (e.g., podoplanin and CD31) may be useful for the differential diagnosis of in situ-like architecture in the metastatic tumors." (PMID 33593410, 2021).
alopecia (5 papers, 2012 to 2022). Hair loss usually from the scalp. "Heterozygous XPorcn-ex3-7flox/X;Krt14-Cre/- females had barely detectable hair loss, but males with Krt14-Cre-driven Porcn deletion had large areas of thin skin with alopecia." (PMID 22412863, 2012). "Med1 controls epidermal lineages in skin, in which Med1 ablation in keratin 14 (Krt14) expressing epithelia enhances epidermal and sebaceous lineages while abolishing hair fate resulting in alopecia." (PMID 33255698, 2020). "Mesenchyme-specific Prx-Cre-driven inactivation of Porcn produces FDH-like limb defects, while ectodermal Krt14-Cre-driven inactivation produces thin skin, alopecia, and abnormal dentition." (PMID 22412863, 2012).
atopic dermatitis (5 papers, 2014 to 2025). "This conditional null mutant will enable more detailed studies on the role of SHARPIN in regulating NFkB and inflammation, while the Krt14-Sharpin-/- provides a new model to study atopic dermatitis." (PMID 32687504, 2020). "Mice expressing a keratin 14–driven constitutively active AHR exhibit skin lesions with itching that are consistent with atopic dermatitis, and one study of Korean Vietnam veterans reported a statistically significant association between the incidence of eczema and Agent Orange exposure." (PMID 24904982, 2014).
COVID-19 (5 papers, 2021 to 2025). A disease caused by infection with severe acute respiratory syndrome coronavirus 2. "By integrating our SARS-CoV-2-infected ALI cultures with a dataset of COVID-19 patients, we also demonstrated that the KRT14 expression was elevated in basal cells from patients with mild but not in severe COVID-19, indicating that the KRT14pos basal cells are important for mild disease phenotype." (PMID 40980495, 2025). "We also demonstrated that the KRT14 and KRT6A expression was elevated in basal cells from patients with mild COVID-19 but not in healthy or severe COVID-19 patients, supporting the potential role of the KRT14pos basal cells in mild disease phenotype." (PMID 40980495, 2025).
gastric cancer (5 papers, 2016 to 2024). A primary or metastatic malignant neoplasm involving the stomach. "Some scholars believe that PADI4 promotes the occurrence and development of gastric cancer by up-regulating TNF-α, CXCR2, and KRT14 in MNK-45 cells and SGC 7901 cells." (PMID 37804426, 2023). "PADI4 plays a role in gastric cancer by upregulating the expression of C-X-C motif chemokine receptor 2 (CXCR2), keratin 14 (KRT14), and tumor necrosis factor (TNF-α)." (PMID 37804426, 2023). "In gastric carcinoma, PAD4 upregulates C-X-C chemokine receptor 2 (CXCR2), keratin 14 (KRT14) and tumour necrosis factor-α (TNF-α) expression levels." (PMID 28587234, 2017).
idiopathic pulmonary fibrosis (5 papers, 2016 to 2025). Idiopathic pulmonary fibrosis (IPF) is a nonneoplastic pulmonary disease that is characterized by the formation of scar tissue within the lungs in the absence of any known cause. "Increased KRT5 and KRT14 expression has also been reported in the alveolar regions in idiopathic pulmonary fibrosis (IPF)." (PMID 27423691, 2016).
lung squamous cell carcinoma (5 papers, 2015 to 2023). "Similarly, in our study, the corresponding KRT14 transcripts were elevated in lung squamous cell carcinoma." (PMID 36949761, 2023). "The immunohistochemistry experiments on lung squamous cell carcinoma show that the lung tissues SOX2, KRT 5, KRT14, EPCAM and PD-L1 have a significant expression." (PMID 36056339, 2022). "Positive staining for Keratin 5, Keratin 6, Keratin 14, or TP63 can indicate squamous cell carcinomas of the lung." (PMID 25955027, 2015). "Therefore, we selected SOX2, KRT5 and KRT14 stemness gene proteins, PD-L1 immune related proteins, vimentin protein, and EpCAM protein, all of which influence epithelial carcinogenesis, to explore whether the mechanism at the cell level corresponds to lung squamous cell carcinoma pathogenesis." (PMID 36056339, 2022).
basal cell carcinoma (4 papers, 2016 to 2023). A carcinoma involving the basal cells. "Previous studies have shown that overexpression of Shh in Krt14(+) epidermal progenitors during development results in the formation of Basal cell carcinoma (BCC)-like epidermal hyperplasia and leads to death of the newborn mice." (PMID 27414999, 2016).
invasive breast carcinoma (4 papers, 2012 to 2023). A carcinoma that infiltrates the breast parenchyma. "We demonstrated the utility of this assay in several applications including demonstration of the existence of a layer of normal myoepithelial KRT14 expressing cells that separate HER2+ cancer cells from the stromal and immune microenvironment in HER2+ invasive breast cancer." (PMID 29184166, 2017).
Naegeli-Franceschetti-Jadassohn syndrome (4 papers, 2017 to 2025). Naegeli-Franceschetti-Jadassohn (NFJ) syndrome is a rare ectodermal dysplasia that affects the skin, sweat glands, nails, and teeth. "This disorder shares an autosomal dominant mutation in the KRT14 gene located on chromosome 17q11.2-q21 with Naegeli-Franceschetti-Jadassohn Syndrome (NFJS) and can be caused by either frameshift or nonsense mutations." (PMID 29201043, 2017). "Our findings confirm that NFJ syndrome is linked to mutations in the KRT14 gene, particularly within the E1/V1-encoding region, generating a premature termination codon (PTC) close to the KRT14 translation initiation site." (PMID 40093016, 2025). "Naegeli-Franceschetti-Jadassohn syndrome (NFJS), also recognized as Naegeli Syndrome, is a distinctive autosomal dominant disorder that arises from mutations in Keratin 14 (KRT14) gene, disrupting the normal development and differentiation of ectodermal tissues." (PMID 40093016, 2025). "Naegeli-Franceschetti-Jadassohn syndrome (NFJS), also known as Naegeli Syndrome, is a rare autosomal dominant ectodermal dysplasia characterized by mutations in the KRT14 gene." (PMID 40093016, 2025). "Mutations in the KRT14 gene are associated with Naegeli-Franceschetti-Jadassohn syndrome (NFJS)." (PMID 40093016, 2025). "The Naegeli-Franceschetti-Jadassohn syndrome (OMIM #161000) due to heterozygous pathogenic variants in the keratin-14 gene (KRT14) is distinguished, as it does not present leukoplakia, bone marrow disease, and an increased risk of malignancy." (PMID 35328050, 2022).
Obesity (4 papers, 2016 to 2021). Accumulation of substantial excess body fat. "On the other hand, transgenic Apln mice that express apelin under the transcriptional control of the keratin 14 promoter are protected from obesity and show a reduced endothelial permeability." (PMID 34658910, 2021). "TP73, PIK3R2, SLC9A3R1, KRT5, KRT14 and TFAP2C are novel biomarkers for pathogenesis of obesity associated type 2 diabetes mellitus." (PMID 33902539, 2021).
oral squamous cell carcinoma (4 papers, 2006 to 2024). "Moreover, transcriptional up-regulation of KRT14, and down-regulation of KRT15 and KRT19 was observed in oral squamous cell carcinoma (OSCC)." (PMID 36949761, 2023). "In addition, the suppression of vimentin in oral squamous cell carcinoma cells corresponds with the depletion of KRT14 and KRT5 and reduced tumorigenicity, potentially through vimentin-mediated ΔNp63 silencing, as an upstream regulator of KRT14." (PMID 39408880, 2024).
cleft palate (3 papers, 2009 to 2023). Cleft palate is a fissure type embryopathy that affects the soft and hard palate to varying degrees. "Another study suggested that the canonical Wnt signaling via ß-Catenin is responsible for the MEE-specific Tgfb3 gene expression, since deletion of the Ctnnb1 gene by a commonly used Keratin 14-Cre (K14Cre) mouse line almost completely abolished Tgfb3 expression in the MEE resulting in cleft palate." (PMID 37250135, 2023). "While no Cre-driver is perfectly efficient, Wnt1-Cre and Krt14-Cre have been used in multiple conditional-knockout models of cleft palate, and both ablate Ranbp1 efficiently in their appropriate compartments." (PMID 36790128, 2023).
head and neck squamous cell carcinoma (3 papers, 2007 to 2024). A squamous cell carcinoma that arises from any of the following anatomic sites: lip and oral cavity, nasal cavity, paranasal sinuses, pharynx, larynx, and salivary glands. "One cluster included Keratin 14, 17 and LY6D; Keratin 17 is a known human basal-like tumor marker, while LY6D is a member of the Ly6 family of glycosylphosphatidylinositol (GPI)-anchored proteins that is highly expressed in head and neck squamous cell carcinomas." (PMID 17493263, 2007).
influenza (3 papers, 2012 to 2025). An acute viral infection of the respiratory tract, occurring in isolated cases, in epidemics, or in pandemics; it is caused by serologically different strains of viruses (influenzaviruses) designated A, B, and C, has a 3-day incubation period, and usually lasts for 3 to 10 days. "Basal cells or basal cell progenitors have been shown to be contributors to distal lung regeneration following influenza infection, and keratin-14-positive cell “pods” can be identified in normal and regenerating adult distal lungs." (PMID 35280447, 2021).
ischemic stroke (3 papers, 2024 to 2026). A stroke disorder caused by obstruction of blood flow to the brain, due to thrombotic (local blood clot formation) or embolic (due to a blood clot or other material traveling from another site) event. "Interestingly, 203 upregulated and 212 downregulated genes, including Krt5, Krt14, Col17a1, and Pgam1‐ps1, were shared between EC‐specific KO and Vasculotide‐treated mice, indicating mutual pathways underlying the endothelial EphA4/Tie2 axis following ischemic stroke." (PMID 41164967, 2026).
keratoconus (3 papers, 2021 to 2025). A degenerative, structural disorder of the eye, characterized by a cone-shaped protrusion of the cornea. "Our study further confirmed that feature genes such as the S100A8/A9 complex, KRT14, and KRT15 were significantly associated with the increased risk of keratoconus, and alterations in these genes were closely related to corneal structural stability, mechanical strength, and disease progression." (PMID 40426861, 2025).
lung adenocarcinoma (3 papers, 2021 to 2024). A carcinoma that arises from the lung and is characterized by the presence of malignant glandular epithelial cells. "In addition, keratin 14 is correlated with nodal metastasis and unfavorable prognosis in human lung adenocarcinoma via Gkn1 induction." (PMID 36949761, 2023). "The prognosis of patients with lung adenocarcinoma was significantly affected by six genes (KRT6A, VEGFC, KRT14, KRT17, SNORA12, and KRT81) related to FSTL3." (PMID 38240936, 2024). "Concurrently, we will delve into the interactions between FSTL3 and other pertinent genes, such as KRT6A, VEGFC, KRT14, KRT17, SNORA12, and KRT81, to enhance our understanding of its role in lung adenocarcinoma progression and to pinpoint novel therapeutic targets." (PMID 38240936, 2024).
metastatic melanoma (3 papers, 2018 to 2022). A melanoma that has spread from its primary site to another anatomic site. "Our study found that genes involved in the biological processes of desmosome organization (GO: 0002934) and hemidesmosome assembly (GO: 00031581) in metastatic melanomas, including JUP, PKP3, KRT14, and KRT5, were inhibited." (PMID 29377892, 2018).
tongue cancer (3 papers, 2019 to 2022). A malignant neoplasm affecting the tongue. "The cancer organoids mimicked the histological features of tongue cancer tissue as evidenced by the expression patterns of markers such as Ki-67 and Krt14." (PMID 34785704, 2021).
ameloblastoma (2 papers, 2020 to 2024). The most common odontogenic tumor, arising from the epithelial component of the embryonic tooth and usually affecting the molar-ramus region of the mandible or maxilla. "Epithelial cells expressed the dental epithelium marker Keratin 14 (Krt14) in an inhomogeneous manner, as highly Krt14-expressing, follicular areas were alternated with Krt14-negative regions in the ameloblastoma epithelium." (PMID 32155948, 2020).